NME2 (NME/NM23 nucleoside diphosphate kinase 2)
Description:
Catalyzes the transfer of a gamma-phosphoryl group from a nucleoside triphosphate, mainly ATP, to a nucleoside diphosphate via a ping-pong mechanism involving a phosphohistidine intermediate, therefore contributing to the nucleoside triphosphate homeostasis. Also functions as a histidine protein kinase by transferring the phosphoryl group from the phosphohistidine intermediate to a histidine residue in target proteins. Phosphorylates the GNB1 subunit of heterotrimeric G proteins at 'His-266', generating a high-energy phosphate group that promotes GTP formation and enables receptor-independent activation of heterotrimeric G proteins (By similarity). Also phosphorylates KCNN4 at 'His-358', leading to activation of its intermediate conductance calcium-activated potassium channel activity, Ca(2+) influx, and subsequent activation of B and T cells. Additionally involved in transcriptional regulation through direct DNA binding and chromatin remodeling. In this context, functions as a single-stranded DNA binding protein that binds and stabilizes the G-quadruplex (G4) structures within the nuclease hypersensitive element (NHE) III(1) region of the MYC gene promoter, facilitating recruitment of additional single-strand DNA binding proteins and activation of MYC transcription. G4 DNA-binding activity is independent of its nucleoside diphosphate kinase function and recognizes both folded and unfolded G4 structures. With NME1, may regulate acetyl-CoA (AcCoA) usage between histone acetylation and fatty acid synthesis by targeting AcCoA release at ATP-rich, HAT-associated chromatin regions (By similarity). Also negatively regulates Rho activity by interacting with AKAP13/LBC.
Synonyms: NDPK B; NDK2; NM23B; NM23-H2; NDPKB; NDKB; NDPK-B; PUF
Tractability: Small molecule: a structure with a bound ligand is known; a high-quality ligand is known; it has a binding pocket of medium quality. Antibody: its Gene Ontology location is reachable by antibodies, with high confidence. PROTAC: ubiquitination databases record sites on it; a small molecule that binds it is known.
Target class: Enzyme
Gene: Protein-coding gene on chromosome 17 (51,163,013 to 51,171,749, forward strand). Ensembl gene ENSG00000243678.
Subcellular location: Cytoplasm; Nucleus; Cell projection, lamellipodium; Cell projection, ruffle; Cytoplasm (Isoform 1); Cytoplasm, perinuclear region; Cytoplasm (Isoform 3)
Subcellular location (Human Protein Atlas): Cytosol
Pathways (Reactome):
Drug ADME: Azathioprine ADME; Ribavirin ADME
Immune System: Neutrophil degranulation
Metabolism: Interconversion of nucleotide di- and triphosphates
Gene Ontology:
Molecular function: DNA binding; DNA-binding transcription activator activity; G-quadruplex DNA binding; GDP binding; identical protein binding; kinase activity; nuclease activity; nucleoside diphosphate kinase activity; protein binding; protein histidine kinase activity
Biological process: integrin-mediated signaling pathway; ITP biosynthetic process; negative regulation of apoptotic process; nucleoside triphosphate biosynthetic process; positive regulation of DNA-templated transcription; positive regulation of DNA-templated transcription initiation; positive regulation of epithelial cell proliferation; positive regulation of keratinocyte differentiation; positive regulation of transcription by RNA polymerase II; regulation of epidermis development; cell adhesion; GTP biosynthetic process; CTP biosynthetic process; nucleotide biosynthetic process; UTP biosynthetic process
Cellular component: cell periphery; cytoplasm; cytosol; extracellular exosome; focal adhesion; lamellipodium; nucleus; ruffle; extracellular region; ficolin-1-rich granule lumen; secretory granule lumen; perinuclear region of cytoplasm
Genetic constraint (gnomAD): Loss-of-function variants: 18 observed, 17.91 expected, observed/expected ratio (o/e) 1, 90% interval 0.69 to 1.49. The upper end of that interval is the gene's LOEUF score, 1.49, which puts it in group 6 of 6, group 1 being the genes least tolerant of losing a copy. Missense variants: 159 observed, 200.63 expected, observed/expected ratio (o/e) 0.79, 90% interval 0.7 to 0.9. Synonymous variants: 72 observed, 73.95 expected, observed/expected ratio (o/e) 0.97, 90% interval 0.8 to 1.18.
Homologues: Orthologues: mouse Nme2 (98% identical), rat Nme2 (98% identical), pig NME2 (93% identical), guinea pig NME2 (93% identical), tropical clawed frog nme2 (86% identical). Paralogues in human: NME1 (87% identical), NME3 (62% identical), NME4 (54% identical), NME5 (30% identical), NME6 (30% identical), NME7 (30% identical), NME8 (29% identical), NME9 (12% identical).
Diseases named in the same sentence as NME2 in open-access papers:
NME2 is named in the same sentence as 69 diseases in open-access papers, as found by Europe PMC text mining. Sharing a sentence is not in itself a finding about the gene and the disease. The quoted sentences say what the papers report.
breast carcinoma (16 papers, 2007 to 2025). "Previous studies have reported that overexpression of NME2 repressed metastasis of human oral squamous cell carcinoma, breast cancer and mouse melanoma cells." (PMID 38605343, 2024). "Different EV fractions such as microvesicles or medium EVs (mEVs) and small EVs (sEVs), the best examples of which are exosomes, were isolated from the supernatant of NME1 and NME2 overexpressing breast carcinoma cells." (PMID 36010906, 2022). "Our aim was to understand how vesicular NME1 and NME2 released by breast cancer cells influence the tumour microenvironment." (PMID 36010906, 2022). "Next, we aimed to understand how extracellular vesicular NME1 and NME2 released by breast cancer cells influence the tumour microenvironment." (PMID 36010906, 2022). "Next, we treated normal skin fibroblasts by a mixture of microvesicles and small EVs from NME1 or NME2 overexpressing breast carcinoma cells and then examined their effect on the RNA pool of fibroblasts." (PMID 36010906, 2022). "To investigate the functional consequences of genetically modifying expression of NME1 and NME2 in MCF10DCIS.com breast carcinoma cells, we studied their cell–cell adhesion properties." (PMID 33918324, 2021). "At this stage, information regarding the relative expression of NME1 and NME2 and stoichiometry of NME1/NME2 hetero-hexamers in different breast cancer cells is missing." (PMID 34012098, 2021). "In particular, the NME2 product inhibits metastasis of breast cancer and lung cancer." (PMID 33424926, 2020). "The potential implication of NME1 and its close relative NME2 protein, during the invasive DCIS-to-IBC switch during breast cancer progression has been overlooked." (PMID 34012098, 2021). "Of note, NME2 is an upstream regulator of CTSK, a protease primarily expressed in osteoclasts which is involved in ECM degradation and bone remodeling and has been found to be expressed in numerous cancers including breast carcinoma." (PMID 39939916, 2025). "Overexpression of NME1, but not its highly related isoform NME2, has been reported to suppress cell migration in multiple highly invasive breast cancer cell lines." (PMID 35259022, 2022). "A meta-analysis of 278 patients with colon cancer, 177 with breast cancer, 137 with ovarian cancer and 77 with lung cancer also found a reduced level of NME2 expression in metastatic cancer as compared with non-metastatic cancer." (PMID 25700270, 2015). "Collectively, these data indicate that metastasis-suppressor NME1, but not NME2, controls the endocytic clearance and surface exposure of MT1-MMP in various breast cancer cell lines." (PMID 34012098, 2021). "NME expression was investigated by IHC analysis on whole sections and on a tissue microarray (TMA) of synchronous DCIS and IBC foci from 156 breast cancer patient samples using specific NME1 pAb and NME2 mAb with no cross-reactivity." (PMID 34012098, 2021).
lung cancer (9 papers, 2014 to 2024). A malignant neoplasm involving the lung. "NME2 expression is associated with a bad prognosis in lung cancer, HCC, BCa, colorectal carcinoma, neuroblastoma, prostate cancer, gastric cancer, and chronic myeloid leukemia has been reported to inhibit cell migration and invasion." (PMID 39063217, 2024). "In A549 cell line, the NME2 downregulation causes transcriptional de-repression of vinculin, thus promoting lung cancer metastasis." (PMID 34628473, 2021). "In lung cancer, NME2 regulates focal adhesion function through its binding to the vinculin promoter, inducing a decrease in vinculin expression at the RNA and protein level." (PMID 39063217, 2024). "The NME2 gene can act as a metastasis suppressor by altering telomere function and telomere length in lung cancer and fibroblasts." (PMID 30857150, 2019). "Herein, our functional analyses in zebrafish and nude mice showed that reduced expression of NME2 promotes metastatic dissemination of lung cancer cells." (PMID 25249619, 2014). "We next probed if NME2 depletion promoted metastatic dissemination of lung cancer cells in an experimental model of metastasis in nude mice." (PMID 25249619, 2014). "Together, we demonstrate that reduced NME2 levels lead to transcriptional de-repression of vinculin and regulate lung cancer metastasis." (PMID 25249619, 2014). "We investigated the molecular mechanisms of NME2 function through genomic, cellular and molecular studies, including model systems and validation in tumor/metastatic lymph node tissue obtained from lung cancer patients." (PMID 25249619, 2014). "In line, enhanced metastasis of NME2-depleted lung cancer cells was found in zebrafish and nude mice tumor models." (PMID 25249619, 2014). "In this report, we identified a key MSG, NME2, from a pool of >30 MSGs through analysis of tumor transcriptomes, overall patient survival data and lymph node metastases in lung cancer patients." (PMID 25249619, 2014). "However, a metastasis suppressor role of NME2 has been demonstrated in BCa, lung cancer, oral squamous carcinoma, melanoma, gastric cancer, endometrial cancer, HCC, thyroid carcinoma, and osteosarcoma." (PMID 39063217, 2024). "Therefore, a decreased expression of NME2 in lung cancer led to enhanced transcription of vinculin and an increase in cell migration and invasion." (PMID 39063217, 2024). "Moreover, it has been reported that CARMA3 promotes cancer stemness and metastasis through NF-κB-driven miR-182 expression and negative regulation of NME2 in non–small cell lung cancer (NSCLC)." (PMID 34885061, 2021). "In order to understand the role played by NME2-regulatory network in metastasis, we asked whether expression of the 64 NME2 target genes related to progression of lung cancer." (PMID 25249619, 2014). "Importantly, to validate our observation in different lung cancer lines, we found increased vinculin levels upon NME2 knockdown in H157 cells, another non-small cell lung carcinoma line." (PMID 25249619, 2014). "Interestingly, GLIS2, another regulatory target of NME2, has been demonstrated to function as a negative regulator of Wnt/beta-catenin signaling pathway and was crucial for lung cancer metastasis to brain." (PMID 25249619, 2014). "Correspondingly, direct demonstration of NME2 action as a metastasis suppressor in lung cancer has been lacking." (PMID 25249619, 2014).
gastric cancer (8 papers, 2015 to 2024). A primary or metastatic malignant neoplasm involving the stomach. "The sequencing results showed that the two alleles of NME2 gene were knocked out in gastric cancer stem-like cells." (PMID 34628473, 2021). "Subsequently, NME2 expression is associated with the well-differentiated and less invasive histology of gastric cancer." (PMID 30621584, 2019). "Because of these diverse NME2 activities on different cancer types, we analyzed tissues surgically removed from patients with gastric cancer and associated the NME2 expression in these tissues with their pathological characteristics." (PMID 25700270, 2015). "Using a tissue chip technology and immunohistochemistry, we demonstrated that NME2 expression was associated with levels of differentiation of gastric cancer cells and their metastasis into the lymph nodes." (PMID 25700270, 2015). "As a result, NME2 expression is associated with the well differentiated and less invasitve histology of gastric cancer." (PMID 25700270, 2015). "NME2 could, therefore, severe as a risk marker for gastric cancer invasiveness and a potential new target for gene therapy to enhance or induce NME2 expression." (PMID 25700270, 2015). "In gastric cancer, NME2 is highly expressed in well-differentiated and less invasive tissue, suggesting a negative correlation between NME2 and cancer progression." (PMID 39063217, 2024). "A recent study showed that NME2 is upregulated in gastric cancer cell lines, where it maintains the stemness of gastric cancer cells by activating anti-apoptotic genes." (PMID 39063217, 2024). "The previous study of our laboratory revealed that NME2 is required for the maintenance of gastric cancer stem-like cell stemness." (PMID 36153608, 2022). "NME2 promoted the proliferation and suppressed apoptosis of gastric cancer stem-like cells, thus being involved in tumorigenesis of gastric cancer." (PMID 34628473, 2021). "Transcription factor NME2 was vital for the maintenance of gastric cancer stem-like cells via regulating anti-apoptosis pathway and promoting stemness-associated genes’ expressions." (PMID 34628473, 2021). "The results demonstrated that the NME2 knockdown significantly increased the caspase 3/7 activity of gastric cancer stem-like cells compared with the control, while the caspase 3/7 activity of the NME2-rescue cells was comparable to that of the control." (PMID 34628473, 2021). "The in vitro and in vivo data revealed that NME2 was required for the maintenance of gastric cancer stem-like cell stemness by promoting the expressions of anti-apoptosis genes." (PMID 34628473, 2021). "NME1 play a potential role to regulated neuroblastoma or hepatocellular carcinoma pathogenesis and NME2 can inhibit gastric cancer metastasis." (PMID 34748517, 2021). "Then to evaluate the role of NME2 in regulating the stemness of gastric cancer stem-like cells, the expression levels of cancer stemness genes were examined." (PMID 34628473, 2021). "Collectively, NME2 was critical for the maintenance of stemness of gastric cancer stem-like cells via promoting the expression of stemness-associated transcriptional factors (c-Myc, LGR5, ALDH1, and Nanog) and anti-apoptosis genes (RIPK1, STARD5, and LIMS1)." (PMID 34628473, 2021). "Taken together, these findings demonstrated that NME2 was critical for the maintenance of stemness of gastric cancer stem-like cells from solid tumors of gastric cancer patients by suppressing apoptosis of CSCs." (PMID 34628473, 2021). "In the present study, the results indicated that the transcription factor NME2 played a positive role in the maintenance of the stemness of gastric cancer stem-like cells sorted from gastric cancer patients." (PMID 34628473, 2021). "Western blots generated the similar results, suggesting that NME2 played an important role in gastric cancer stem-like cells." (PMID 34628473, 2021).
gastric cancer (continued). "Based on the immunohistochemical analysis, it was revealed NME2 played a positive role in anti-apoptosis of gastric cancer stem-like cells." (PMID 34628473, 2021). "The results of cell counting and MTS assays showed that NME2 played an important role in the proliferation and growth of gastric cancer stem-like cells sorted from solid tumors." (PMID 34628473, 2021). "In vitro and in vivo data revealed that NME2 was crucial for maintaining the stemness of gastric cancer stem cells by enhancing the expression of anti-apoptosis genes." (PMID 34628473, 2021). "Previous studies have shown that an overexpression of NME2 reduces the migration and invasion of gastric cancer cells to the cellular matrix in vivo and in vitro." (PMID 30621584, 2019). "This pathology study was complemented by in vitro experiments, where we examined rates of proliferation, migration and invasion of gastric cancer cells that have been stably transfected with a human NME2 cDNA to overexpress its product." (PMID 25700270, 2015). "Here, we provide several lines of evidence that NME2 limits the proliferation, migration and invasion to the extracellular matrix of gastric cancer cells." (PMID 25700270, 2015). "Our results identified gastric cancer cells as sensitive to over-expressed NME2, but a critical question remains as what regulates these diverse NME2 activities among different types of cancer cells." (PMID 25700270, 2015). "We have investigated the relationship between the NME2 expression and characteristics of gastric cancer in tissues surgically removed from patients and in cultured cells from two known gastric cancer lines." (PMID 25700270, 2015). "In summary, we have demonstrated that an overexpression of NME2 reduces the migration and invasion of gastric cancer cells to the cellular matrix in vitro." (PMID 25700270, 2015). "First, a higher level of NME2 expression is found in well-differentiated and less invasive tissue from gastric cancer surgically removed before chemotherapy and radiotherapy in a large patient cohort." (PMID 25700270, 2015). "However, overexpression of NME2 in squamous cell carcinoma and in gastric cancer decreases metastasis and cell proliferation, indicating NME2 has metastatic potential." (PMID 39063217, 2024). "Based on the gene expression profile of NME2 in the cancerous tissues of cancer patients and healthy donors using the Cancer Genome Atlas (TCGA) database, NME2 was significantly upregulated in the cancerous tissues of gastric cancer patients compared with that of the healthy donors." (PMID 36153608, 2022). "The results showed that NME2 was upregulated in gastric cancer stem-like cells." (PMID 34628473, 2021). "Interestingly, our previous study reveals that transcription factor NME2 (NME/NM23 nucleoside diphosphate kinase 2) is a master suppressor for apoptosis of gastric cancer cells via regulating the expressions of miRNA and protein-encoding genes." (PMID 34628473, 2021). "Thus, the influence of NME2 on the expressions of these genes in gastric cancer stem-like cells sorted from the solid tumors of gastric cancer patients was characterized." (PMID 34628473, 2021). "We hypothesize that NME2 (Nucleoside Diphosphate Kinase 2), which has previously been considered as an anti-metastatic gene, plays a role in the invasiveness of gastric cancer cells." (PMID 25700270, 2015). "Third, in contrast to a minimal effect on the proliferation of gastric cancer cells, the overexpression of NME2 results a significant reduction in cell migration and invasion through the collagen matrix as demonstrated in three distinct, but complementary assays." (PMID 25700270, 2015). "To further examine the association of NME2 expression with pathological characteristics of gastric cancer cells, we studied cells from the BGC823 and MKN45 gastric cancer lines, which expressed NME2 weakly at a level compared to poorly differentiated cancer tissue." (PMID 25700270, 2015).